CD4 (CD4 molecule)
Diseases named in the same sentence as CD4 in open-access papers (continued):
Sharing a sentence is not in itself a finding about the gene and the disease.
T cell deficiency (continued). "CD8+ T cell deficiency and an increased CD4/CD8 ratio are features of many human chronic autoimmune diseases." (PMID 33479266, 2021). "In this study, we also aimed to investigate a putative role of the HIV-related CD4 T-cell deficiency in promoting respiratory virus-associated infection." (PMID 32953200, 2020). "In contrast, little is known about the epidemiology of respiratory viruses in HIV-infected patients, especially those admitted to the ICU, and the prevalence of respiratory viruses according to the CD4 T-cell deficiency." (PMID 32953200, 2020). "In contrast, CD127 surface densities when defining ILCs by IL-18Rα were significantly reduced in two settings of CD4 T cell deficiency." (PMID 30262807, 2018). "Upon LCMV infection in the periphery, CD4 T cell deficiency is associated with sustained high viral load, which in turn, upregulates checkpoint inhibitory receptors (e.g., PD-1) on virus-specific CD8 T cells." (PMID 30372487, 2018). "LCK deficiency causes atypical EV with CD4 T cell deficiency as well as recurrent pneumonia and severe warts complicated by non-melanoma skin cancer." (PMID 28674531, 2017). "The vast majority of T cell deficiency conditions will have low T cell numbers or at least low CD4/CD45RA (naïve) T cell counts." (PMID 28674531, 2017). "Several studies have examined the role of CD8+ T-cells during primary infection, yet the role of CD8+ T-cells, particularly in the setting of CD4+ T-cell deficiency, remains controversial." (PMID 27242785, 2016). "CD8+ T-cells recruited to the oral mucosa of the transgenic mice limited the proliferation of C. albicans in these conditions of CD4+ T-cell deficiency." (PMID 26110288, 2015). "Our results suggest that the immune stimulation by SGs goes beyond the Th1 immune response because our vaccination strategy is still effective in condition of CD4+ T cell deficiency." (PMID 26322039, 2015). "While the effect of CD4+ T cell deficiency on bioluminescent signal in the cervical lymph nodes was significant but partial, the effect on the bioluminescent signal in the abdomen was total." (PMID 21283759, 2011). "Meanwhile, the percentage of samples with severe CD4 T-cell deficiency (defined as below 15%) dropped from 20% in 1997 to 6.3% in 2007." (PMID 19681795, 2009). "Also, among the extra-renal manifestations, there were leukopenia and T-cell deficiency (CD4+ and CD8+)." (PMID 40004207, 2025). "Thus, due to disrupted CD4/HLA class II interactions in the thymus, individuals with HLA class II deficiency have profound CD4+ T cell deficiency (10–20-fold reduction) and are consequently susceptible to a broad range of pathogens." (PMID 38557723, 2024). "To further understand the mechanisms of primary NMI-infection induced protective immunity, we examined if B cell, T cell, CD4+ T cell or CD8+ T cell deficiency in mice will significantly affect primary NMI-infection induced protective immunity against NMI reinfection." (PMID 39469719, 2024). "Importantly, evidence of profound T cell deficiency, low CD4+ T cell counts, low relative numbers of CD4+ T cells in relation to the child’s age, and absent T cell proliferation are exclusion criteria for CVID." (PMID 39337487, 2024). "Thus, in addition to CD4 T cell-deficiency, elevated IFN-γ concentrations also contribute to downregulation of CD127 and CXCR3 on memory P14 T cells in MHCII−/− mice." (PMID 38806459, 2024). "Subsequently, T-cell deficiency with decreased CD4 and CD8 cells was diagnosed." (PMID 36658659, 2023). "However, a CD4+ T cell population is required for the development of both cell-mediated and humoral immunity, since CD4+ T cell deficiency results in delayed viral clearance and increased mortality, as well as a lack of development of OPXV-specific antibodies." (PMID 36986285, 2023).
T cell deficiency (continued). "In conclusion, HIV infection impaired the induced innate immune response and nadir CD4+ T-cell count might not only reflect T-cell deficiency but also impairment of the innate immune response." (PMID 36059528, 2022). "However, in the process of long-term homozygous breeding, lc3b−/− mice exhibited an H2-Aa spontaneous point mutation and consequent MHC II loss and CD4+ T-cell deficiency." (PMID 35309308, 2022). "We therefore hypothesized that vaccination with C. neoformans Δsgl1 must induce protectively polarized T cells even in condition of CD4+ or CD8+ T cell deficiency." (PMID 36229573, 2022). "On the other hand, CD4 T cell deficiency was associated with a significantly enhanced PE-induced vasoconstriction of ICAs that may result from increased sensitivity to PE or enhanced intrinsic smooth muscle contractility." (PMID 34220551, 2021). "We hypothesized that CD4 T cell deficiency in pregnancy would result in ICA dysregulation, including enhanced ICA vasoconstriction." (PMID 34220551, 2021). "These cells may play an important role in protection against C. albicans in individuals with CD4+ T cell deficiency, for instance in HIV-positive patients." (PMID 32887412, 2020). "As we did not include a comparative non-HIV population, we rather examined whether or not the rate of viral documentation varied along with the level of CD4 T-cell deficiency." (PMID 32953200, 2020). "It shows that therapeutic vaccination may be feasible in situations where patients manifest with CD4 T-cell deficiency, for instance due to disease or medical immune suppression." (PMID 31333674, 2019). "Furthermore, acquired CD4 T cell deficiency, modeled by delaying systemic CD4 T cell depletion, also impacted the differentiation of CD8 bTRM and decreased the ability of these cells to control reinfection." (PMID 31514273, 2019). "Hence, neither MHC class II signaling nor CD4 T-helper cells were required for PCI-mediated stimulation of CD8 T-cell responses, and the two tested models of CD4 T-cell deficiency were comparable." (PMID 31333674, 2019). "Acquired CD4 T cell deficiency, modeled by delaying systemic CD4 T cell depletion until MuPyV-specific CD8 T cells have infiltrated the brain, impacted the stability of CD8 bTRM, impaired their effector response to reinfection, and rendered their maintenance dependent on circulating CD8 T cells." (PMID 30372487, 2018). "Moreover, in both acute spinal cord injury and an ALS mouse model, CD4+ T cell deficiency accelerates the degenerative process." (PMID 22073221, 2011). "However, the CD4+ T-cell deficiency in HIV-infected children likely impairs mounting an effective memory against vaccines, and secondary vaccine failure due to a decline in vaccine-induced antibody over time has been described." (PMID 18060056, 2007). "Case reports and a small case-control study have reported clinically significant CMV and Pneumocystis jiroveci infection in individuals with elevated absolute CD4+ T cell counts, and pathogen-specific CD4+ T cell deficiency has been suggested to persist in these patients." (PMID 17388662, 2007). "Therefore, we wanted to determine the dynamics of dendritic cell populations that may dictate the cross-presentation following fungal vaccination during CD4+ T cell deficiency during afferent phase." (PMID 40491915, 2025). "Therefore, we hypothesized that an unrecognized factor, other than CD4 T cell deficiency, is responsible for defective persistence of memory CD8 T cells in MHCII-deficient mice." (PMID 38806459, 2024). "Thus, protection was lost in mice with CD4+ T cell deficiency." (PMID 36732332, 2023). "Besides this potential qualitative CD4 T cell deficiency, an altered CD4 T cells-macrophage crosstalk could also be involved via decreased macrophage ability to contain Cryptococcus spp." (PMID 35425769, 2022). "Thus, the common immunophenotypic denominator for all these patients was CD4+ T-cell deficiency." (PMID 32098969, 2020).
T cell deficiency (continued). "Studies in HIV-infected patients with OPC and in CD4C/HIVMutA Tg mice have shown an influx of CD8+ T-cells to the oral mucosa in response to C. albicans infection, suggesting that this cell population may play a role in limiting oral proliferation in the context of CD4+ T-cell deficiency." (PMID 26110288, 2015). "In contrast, TN and TCM subsets of both CD4+ and CD8+ T cells were decreased, whereas TEMRA subset of CD4+ and CD8+ T cells were markedly increased in patients with syndrome of SIGMD, T cell deficiency, and MAC infection." (PMID 28928736, 2017). "Thus, in parallel, we developed a model of T cell deficiency by antibody depletion of CD8+ and CD4+ T cells prior to primary challenge, confirming T cell depletion by flow cytometry." (PMID 40956633, 2025). "Here we show that chronic interferon-γ signals, not CD4 T cell-deficiency, are responsible for their attrition in MHCII-deficient environments." (PMID 38806459, 2024). "Increased IFN-γ production is therefore a phenotype of MHCII−/− mice that is independent of CD4 T cell-deficiency." (PMID 38806459, 2024). "Because immunosuppression—and in particular T cell deficiency—favors EBV reactivation from its latent B cell reservoir, EBV viremia is frequently detected in (untreated) HIV-infected individuals with advanced disease and low CD4 + T cell counts." (PMID 33633271, 2021). "The patients with CD4+ T cell deficiency on admission who accepted HDIVC showed a better recovery ability of the CD4+ T cell count than those who had not received HDIVC." (PMID 33967773, 2021). "The prevalence of respiratory virus-associated infection did not vary along with the level of the CD4 T-cell deficiency, except for Rhinovirus which was more prevalent in patients with a CD4 lymphocyte count below 200 cells/μL." (PMID 32953200, 2020). "The prevalence of respiratory virus-associated infection did not vary along with the level of the CD4 T-cell deficiency, except for Rhinovirus which was more prevalent in patients with a CD4 lymphocyte count below 200 cells/μL (n = 13 (20%) vs. n = 2 (4%), p < 0.01)." (PMID 32953200, 2020). "Because CD4 T cell deficiency is often an acquired rather than an inherited condition, we asked whether delayed systemic deletion of CD4 T cells affected development of functionally competent CD8 bTRM during MuPyV encephalitis." (PMID 30372487, 2018). "Thus, CD4+ T cell deficiency is not enough to show increased susceptibility." (PMID 33526558, 2021). "However, our previous data did show that, under conditions of CD4+ T cell depletion, the protection induced by GXM in the presence of the SG accumulation may go beyond the Th1 response, since protection was also previously observed under conditions of CD4+ T cell deficiency." (PMID 30940711, 2019).
osteosarcoma (84 papers, 2005 to 2026). A usually aggressive malignant bone-forming mesenchymal neoplasm, predominantly affecting adolescents and young adults. "used ScRNA-seq data to identify natural killer (NK) cell marker genes, finding that low-risk osteosarcoma patients had high levels of infiltrating immune cells, particularly naïve CD4 and CD8 T cells, in an immunosuppressive microenvironment." (PMID 39324133, 2024). "In support of this result, a biomarker experiment study showed that the CD86/CD28 stimulatory pathway associated with activated memory CD4 T cells was dominant in osteosarcoma patients with a good prognosis." (PMID 39081321, 2024). "Our results found significantly higher proportions of naive CD4+ T cells, resting NK cells, M0 macrophages, and neutrophils in high-risk patients with osteosarcoma, suggesting a signature of an immunosuppressive microenvironment." (PMID 36578780, 2022). "In both TARGET and GSE21257 datasets, osteosarcoma patients with high risk had prominently higher proportions in immunosuppressive cells (such as naive CD4+ T cells, resting NK cells, M0 macrophages, and neutrophils)." (PMID 36578780, 2022). "Our analysis showed that children with osteosarcoma at high risk of experiencing hypoxia had an elevated number of CD4 cells, suggesting an immunosuppressive disorder." (PMID 34337075, 2021). "Moreover, the analysis identified alternative splicing events that were co-altered with resting memory CD4 T cells, resting dendritic cells, and activated mast cells, events that may be associated with regulation of the osteosarcoma immune microenvironment." (PMID 37139238, 2023). "Metastatic and recurrent osteosarcoma lesions exhibit a lower proportion of CD4+ and CD8+ TILs than primary lesions." (PMID 39359731, 2024). "In a study of osteosarcoma, anti-PD-1 treatment increased overall survival and decreased intra-tumoral Ki67+Foxp3+CD4+ Treg cells in osteosarcoma-bearing mice, compared with sham-treated control." (PMID 39247203, 2024). "The results of immune-infiltration and immune-phenotype correlation analyses also revealed an essential role of native CD4 T cells and M2 macrophages in the immune microenvironment of osteosarcoma." (PMID 38980440, 2024). "It has been reported that activation of PD-L2/RGMB pathway induces osteosarcoma growth and lung metastasis, and PD-L2 stimulates CD4+ T-helper 1 response through PD-L2/RGMB interaction." (PMID 39042313, 2024). "The bar graph shows that Macrophages M2, Macrophages M0, and CD4 memory resting T cells are the most abundant of these immune cells in the immune microenvironment of all osteosarcoma samples." (PMID 38041020, 2023). "Our data revealed a significant decrease in the ratio of CD4+/CD8+ also the percentage of CD4+ cells in peripheral blood of patients with osteosarcoma compared to patients with GCT and healthy controls." (PMID 37993664, 2023). "The R1.t group was associated with a higher level of mast cells, T CD4+ lymphocytes memory, T CD8+ lymphocytes, and activated NK, in keeping with the microscopic analysis of the samples on the slide as found also in osteosarcoma." (PMID 37444560, 2023). "HOS-CD4/CXCR4 is a human osteosarcoma cell line that expresses the HIV-1 receptor CD4 and its chemokine co-receptor CXCR4 and supports robust HIV-1 replication." (PMID 37509131, 2023). "Here, we found that IL-17 produced by CD4-positive lymphocytes maintains osteosarcoma cells in an undifferentiated state and is required for tumor progression." (PMID 38062130, 2023). "Here, we show that IL-17 likely produced from CD4-positive T cells acts directly on osteosarcoma cells to promote tumor growth by inhibiting osteoblastic differentiation." (PMID 38062130, 2023). "Based on the data, the percentage of CD4 + cells were decreased in patients with osteosarcoma tumors compared to patients with GCT (P = 0.017) and healthy subjects (not significant statistically)." (PMID 37993664, 2023).
osteosarcoma (continued). "CD4-positive cells adjacent to osteosarcoma cells express IL-17, while osteosarcoma cells express the IL-17 receptor IL-17RA." (PMID 38062130, 2023). "In metastatic pediatric sarcomas including osteosarcoma and Ewing sarcoma, adjuvant therapy with recombinant IL-7 was shown to promote immune recovery and CD4 count recovery compared with standard therapy." (PMID 39086683, 2023). "The simultaneous elevation of IFN-γ and TGF-β was detected in Ewing sarcoma and GCT, also the CD4 + /CD8 + ratio was decreased significantly in patients with osteosarcoma compared to GCT tumors." (PMID 37993664, 2023). "Consistently, our analysis connected a lower proportion of infiltrated activated CD4 memory T cells with a worse prognosis in osteosarcoma." (PMID 36330451, 2022). "In human osteosarcoma, elevated expression levels of macrophage and CD4 T-cell markers (defined as CD4/IFNGR2/CD68/CSF1R signature) was associated with favorable neoadjuvant chemotherapy responses." (PMID 36686729, 2022). "In the TARGET‐osteosarcoma cohort, we observed a strong correlation between the LAMP3_DC gene signature and the CD4_C6_FOXP3 and CD4_C5_CXCL13 cellular gene signatures." (PMID 36305631, 2022). "In summary, these results indicated that combination treatment with a c-Myc inhibitor and an anti-PD-1 antibody exhibited a synergistic therapeutic effect in osteosarcoma that was dependent on CD4+ and CD8+ T cells." (PMID 35292660, 2022). "In osteosarcoma, tumor-infiltrating lymphocytes are mainly distributed in the region expressing human leukocyte antigen Class I, whereas CD4+ and CD8+ T cells are mainly clustered at the interface between pulmonary metastases and normal tissues." (PMID 35720360, 2022). "Oppositely, T cells CD4 naïve and macrophages M0 had lowered levels in osteosarcoma compared to normal tissues." (PMID 33748161, 2021). "Baicalin was found to interfere with the human immunodeficiency virus (HIV)-1 envelope glycoprotein (gp120)-mediated fusion with human osteosarcoma cells expressing CD4/CCR5 or CD4/CXCR4." (PMID 34445463, 2021). "Macrophages M0, macrophages M2, T cells CD4 memory resting, T cells CD4 naïve, and B cells naïve account for a large proportion of osteosarcoma immune cell infiltration." (PMID 32190007, 2020). "The results indicated that naive B cells, activated memory CD4 + T cells, follicular helper T cells, resting dendritic cells, activated dendritic cells were independent predictors for osteosarcoma patients." (PMID 33087099, 2020). "Clinical sample results show that the infiltration abundance of CD68 +macrophages and Th1 CD4 + cells was positively correlated with each other and prone to be better prognosis of osteosarcoma and efficacy of neoadjuvant chemotherapy in OSA." (PMID 32850346, 2020). "All of the HIV-positive patients with concurrent osteosarcoma fulfilled the WHO immunological criteria for advanced HIV infection with a CD4 count of less than 350 cells/mm3." (PMID 23762607, 2013). "We next examined the intensity of TILs infiltration in specimens from all 61 osteosarcoma patients, sorted by CD4 and CD8 immunostaining." (PMID 23940627, 2013). "Human osteosarcoma cells modified to express CD4 and CXCR4 (HOS-CD4/CXCR4) support robust HIV-1 replication, which is potently restricted by pre-treatment with IFNβ." (PMID 18389079, 2008). "In an earlier report, we described that CD4/CXCR4 positive human osteosarcoma cells stably expressing NF90ctv were able to induce transcriptional program of antiviral response genes to block HIV-1 replication." (PMID 17565699, 2007). "TIL extracted from rat tumor biopsies demonstrated similar phenotype to human osteosarcoma TIL (predominantly CD4+) and exhibit a highly cytotoxic activity against autologous tumor cells." (PMID 16188028, 2005). "Similar data were observed in rat osteosarcoma model where TIL were characterized by a main CD4+ profile and high lytic activity against allogeneic and autologous tumor cells." (PMID 16188028, 2005).